APOE (apolipoprotein E)
Diseases named in the same sentence as APOE in open-access papers (continued):
Sharing a sentence is not in itself a finding about the gene and the disease.
dementia (continued). "Our study focused on this issue by voxel-wise modeling the nonlinear atrophy trajectories of the whole brain from cognitively normal to dementia in each APOE variant." (PMID 37323144, 2023). "This analysis incorporated plasma pTau217, pTau181, ratio Aβ1–42/ Aβ1–40, Age, Sex, APOE ε4 allele presence, and clinical diagnosis group (cognitively unimpaired, mild cognitive impairment, and dementia)." (PMID 38168408, 2023). "Our findings further expand the results of previously published studies on the walking pace and dementia associations by demonstrating that the APOE ε4 dosage significantly modified the association between walking pace and new-onset dementia." (PMID 36624486, 2023). "Walking pace was inversely associated with new-onset dementia in the general population, especially in younger participants and those with lower APOE ε4 dosage." (PMID 36624486, 2023). "The findings in our two studies are in contrast to a meta-analysis that reported that APOE ε4 carriers are more vulnerable to diabetes-associated dementia." (PMID 37091584, 2023). "The ε4 allele of the apolipoprotein E (APOE ε4) gene is the strongest known genetic risk factor for dementia and cognitive impairment." (PMID 38137058, 2023). "APOE status significantly modified the association (p = 0.04), with stronger associations observed among participants with a lower genetic risk of dementia." (PMID 37605228, 2023). "The Kaplan–Meier survival curves showed that the risk of incident dementia was highest for APOE e4 carries with both lowest tertile of handgrip strength and vitamin D profiles among women and men." (PMID 37246226, 2023). "Specific genetic variants, such as those associated with the APOE gene, are known to increase the risk of developing dementia." (PMID 38074067, 2023). "Cerebrovascular lesions were not significant mediators, and the protective effects of the APOE-ε2 allele against dementia were mediated only by the AD-pathology." (PMID 38115150, 2023). "With the knowledge of the role of APOE-ε4 in metabolism and autophagy signaling, APOE-ε4 has been linked to the effects of long COVID and dementia." (PMID 37238686, 2023). "We found that participants with higher vitamin D and grip strength profiles were associated with lower risk of dementia, and seemed to counteract the adverse effects of APOE e4 genotype on dementia by almost 50%." (PMID 37246226, 2023). "Being in the highest quartile for the inflammatory biomarker score, compared with the lowest quartile, was associated with an increased risk for dementia diagnosis by about 35% (HR 1.349, CI 1.215–1.498) in a fully adjusted model (including APOE)." (PMID 37467176, 2023). "In line with previous studies, we showed that APOE e4 is the strongest risk factor for dementia in LBD." (PMID 37987016, 2023). "Mediation analyses estimated that the percent excess risk of APOE-ε4 on other causes of mortality risk explained by the dementia diagnosis was 24%, which increased to 34% when the sample was restricted to adults who were aged ≤75 years old." (PMID 37434484, 2023). "Cox regression revealed that higher inflammatory biomarker scores were significantly associated with increased dementia risk in a model adjusted for sex, APOE ε4 status, cardiovascular problems at baseline, ethnic background and Townsend Deprivation Index." (PMID 37467176, 2023). "While FAD and APOE are recognized for their significant roles, numerous other genes have been identified that contribute to dementia risk." (PMID 38074067, 2023). "We also tested the casual association between type 2 diabetes and dementia within the APOE ε4-negative subgroup using two-sample MR." (PMID 37091584, 2023). "Our findings suggest that the Aβ peptide is operational in young onset dementia and driven by the APOE ɛ4 allele." (PMID 37090959, 2023). "Among APOE ɛ4 carriers, those who experienced either large BMI loss or large BMI gain had an increased risk of dementia compared with those with stable BMI." (PMID 35921193, 2023).
dementia (continued). "When the participants are clustered based by their APOE variant, people with APOE ε3/ε4 and ε4/ε4 have the highest dementia risk." (PMID 37628615, 2023). "In the Framingham Heart Study (FHS), chronic peripheral inflammation measured with CRP increased the risk for dementia and AD dementia but only in apolipoprotein E (APOE) ε4 carriers." (PMID 37584418, 2023). "The intersection between variations in frequency of the APOE Ɛ4 alleles, and the prevalence of dementia thus becomes important." (PMID 38028602, 2023). "We aimed to investigate the interactions between vitamin D/grip strength and APOE e4 genotype and their association with dementia." (PMID 37246226, 2023). "This study demonstrates the presence of an APOE e4 gene interaction on the associations between dementia severity (CDR-SB) and WMHs in cholinergic pathways." (PMID 36864910, 2023). "More importantly, the inverse association between walking pace and new-onset dementia was significantly attenuated as APOE ε4 dosage or age increased." (PMID 36624486, 2023). "There are three common variants or alleles of the APOE gene, APOE2, APOE3, and APOE4, each associated with varying degrees of dementia risk." (PMID 38074067, 2023). "Dementia risk prediction models that use APOE ε4 status or other clinical markers are shown to provide more predictive ability than the risk tools examined in this study." (PMID 37647064, 2023). "Multiple risk factors predict the progression of MCI to dementia including higher age, APOE ε4 (APOE4) allele, lower educational attainment, and cerebrovascular disease (CVD)." (PMID 37270543, 2023). "In a previous study of 109 PSEN1 E280A mutation carriers, those who had an APOE e4 allele had an earlier age of dementia onset than those who did not5." (PMID 37612284, 2023). "Given that the cholinergic system plays a crucial role in cognitive impairment, this study aimed to identify how APOE status modulates the associations between dementia severity and white matter hyperintensities in cholinergic pathways." (PMID 36864910, 2023). "Summary of significant associations for dementia outcomes using Model 1 in full sample and by APOE status strata." (PMID 37584418, 2023). "In sensitivity analyses with further adjustment for ethnicity and APOE ε4 genotype, the results for all stroke and all-cause dementia were very similar and broadly comparable (eFigure 4, links.lww.com/WNL/C877, eTable 8, links.lww.com/WNL/C878)." (PMID 37290969, 2023). "In MGB Biobank the association of the PRSs are almost only due to AD and dementia cases, and almost entirely due to APOE SNPs." (PMID 37649099, 2023). "Focusing on genetics, others have reported a significant association between lower CR and APOE ε4, a well-established risk factor for dementia." (PMID 37926851, 2023). "A risk factor with low prevalence, such as APOE ε4 homozygosity which is present in only 2-3% of the general population (approximately 4-5% of those with a first-degree family history of dementia), will likely in a high screen fail rate." (PMID 37357285, 2023). "The APOE ε4 allele is an established risk factor for dementia, incident MCI, and rate of conversion from MCI to dementia." (PMID 36900708, 2023). "In support of this, several studies reported that the APOE*ε4 genotype is more strongly associated with dementia in women as compared to men." (PMID 36937877, 2023). "APOE is a well‐established risk factor for AD and has been shown to interact with affective NPSs to influence dementia risk." (PMID 37139261, 2023). "In humans, a decrease in global efficiency is associated with dementia and cognitive impairment in certain patients, and we see it affected in regions where ApoE is known to localize." (PMID 38075287, 2023). "Given its important role in lipid metabolism and AD dementia, it is possible that the association of ApoE level with dementia or cognitive function is modulated by its association with other apolipoproteins." (PMID 37666928, 2023).
dementia (continued). "Previous studies have also shown that healthy lifestyle is associated with slower cognitive decline and a lower risk of dementia, even in the presence of the APOE ε4 allele." (PMID 37636818, 2023). "Of the studied genetic factors, as expected, homozygotes for APOE-ɛ4 had the highest risk of dementia (OR = 7.98)." (PMID 37834213, 2023). "Within the stable weight and weight gain groups, APOE ε3/ε4 and ε4/ε4 variants remain the strongest risk factor for dementia." (PMID 37628615, 2023). "Compared to the APOE-ε3/ε3 genotype, having at least one APOE-ε4 allele increases the risk of cognitive decline and dementia." (PMID 38115150, 2023). "In many populations, the apolipoprotein-ε4 (APOE-ε4) allele increases the risk for several chronic diseases of aging, including dementia and cardiovascular disease; despite these harmful effects at later ages, the APOE-ε4 allele remains prevalent." (PMID 37556539, 2023). "In APOE e4 carriers, increased white matter in cholinergic pathways are associated with greater dementia severity." (PMID 36864910, 2023). "In summary, the present study explored the differences in cognitive performance, brain structure, and function between the cognitively protective APOE ε2 allele and cognitively impaired APOE ε4 allele in non-dementia elderly carriers." (PMID 37636817, 2023). "To check for an effect of mLOY on risk of conversion to all-cause dementia and AD, we fitted Cox proportional-hazards models adjusted by age at sampling and APOE genotype in our prospective cohort of men with MCI (N = 400)." (PMID 36674414, 2023). "The type of APOE allele is a well-known genetic risk factor for dementia, PD and MS, and people with the APOE ε4 allele are at increased risk for all three diseases." (PMID 36797805, 2023). "APOE ε4 allele association with brain atrophy and cognitive decline has been reported in healthy aging individuals and dementia patients." (PMID 37323144, 2023). "Given their conclusions, we judge that prodromal or undiagnosed dementia had little influence on our findings of a robust association of APOE e4 status and cognitive slope." (PMID 36481934, 2023). "APOE is linked to longevity, cardiovascular disease, and neurodegenerative disorders including AD and related dementias." (PMID 37584418, 2023). "The APOE gene polymorphisms are associated with many diseases such as dementia, Parkinson’s disease, epilepsy, and CAD." (PMID 36980959, 2023). "Debates about the ethics of dementia risk prediction have been current since at least the identification of the ApoE e4 allele associated with increased susceptibility to Alzheimer's disease in the early 1990s." (PMID 38439952, 2023). "In association analysis of PRSsum where the MCI group included AD and dementia cases, and the two SNPs defining the APOE alleles were used as covariates, PRSsum was associated with MCI with OR = 1.06 and p-value = 0.2." (PMID 37649099, 2023). "For people with the other APOE variants (ε2/ε2, ε2/ε3, and ε2/ε4, and ε3/ε3), people who lose weight have the highest risk of developing dementia." (PMID 37628615, 2023). "We found that drinking tea had a more beneficial effect in reducing the risk of dementia among populations with less physical activity, older age, APOE carriers, and smokers." (PMID 37483967, 2023). "The mediation effect of the dementia diagnosis on the association between APOE-ε4 status and “Other” causes of mortality increased to 34%." (PMID 37434484, 2023). "In terms of genetic predisposition, earlier studies have reported that individuals with both diabetes and an APOE ε4 allele exhibit more pronounced cortical changes, reductions in cognitive function, and an increased risk for dementia." (PMID 38107512, 2023). "We aimed to investigate the associations of body mass index (BMI) and weight changes with dementia and to explore the role of APOE ɛ4 in these associations." (PMID 35921193, 2023).
dementia (continued). "In contrast, more than ten percent of the global population over the age of 65 is affected with the sporadic form of AD; the ε4 allele of the apolipoprotein E (APOE) gene results in heightened risk, and at least 60 percent of individuals with dementia have AD." (PMID 37508898, 2023). "In our study, we found that snoring, a common condition in older adults, was associated with a lower risk of all-cause dementia and AD, particularly in older individuals and APOE ε4 carriers." (PMID 37873444, 2023). "As well as APOE, recent genome-wide association studies have identified additional single nucleotide polymorphisms (SNPs) significantly associated with dementia risk." (PMID 37605228, 2023). "APOE ɛ4 carrier status has been shown to lead to a high incidence of AD and DLB, but the effect of APOE ɛ4 on the risk of dementia and mortality diminishes or disappears with advanced age." (PMID 36776074, 2023). "Because APOE ε4 is also a cause of dementia (with Z6), this results in overrepresentation of the doomed response types in the low education group in the study sample." (PMID 38435670, 2023). "While the association between mid-life BP and dementia is better known, less is known about the possible mediating role of cerebral microinfarcts when its risk factors (e.g., age and genetics (APOE e4)) are controlled." (PMID 37763020, 2023). "Our findings suggested that combination of high vitamin D and handgrip strength counteracts the risk effect of APOE e4 genotype on dementia by almost 50%." (PMID 37246226, 2023). "Our study confirmed the relationship of APOE gene variants with cognitive impairment in elderly people in our sample, as the risk alleles were more frequently found in the dementia group and were also associated with a lower score on the MMSE cognitive scale." (PMID 36421848, 2022). "The results showed that the interaction between PPI use and APOE ε4 genotype was still present for all-cause dementia (P for interaction = 0.012), and the HR of PPI users among APOE ε4 heterozygote was 1.68 (95% CI, 1.36–2.07; P < 0.001)." (PMID 36045363, 2022). "In a population study of over 75,000 Danes, Rasmussen and Frikke-Schmidt examined plasma ApoE levels and risk of dementia." (PMID 35912085, 2022). "Carriers of APOE-ε4 (n = 281, 29.7%) and GBA mutations (n = 100, 10.3%) had faster cognitive decline and were at higher risk of progression to dementia (APOE-ε4, HR 3.57, P < 0.001; GBA mutations, HR 1.76, P = 0.001) than non-carriers." (PMID 35106798, 2022). "The APOE ε4 genotype is a strong risk factor for dementia and in the present study, APOE ε4 genotypes were associated with weight loss." (PMID 36092692, 2022). "After age stratification, homozygous ApoE ε4 carriers presented the highest risk among all factors for dementia occurrence throughout all age groups." (PMID 36578446, 2022). "We studied the impact of three risk-factors, Apolipoprotein (APOE)-ε4, a family history of dementia, and central obesity, on the CA1, CA2/3, dentate gyrus and subiculum of 158 cognitively healthy adults (38-71 years)." (PMID 35303671, 2022). "In this large prospective cohort study of 495,942 UK adults, we found that glucosamine use was associated with a 10% lower risk of dementia, there were significant additive and multiplicative interactions between glucosamine use and APOE ε4 genotype." (PMID 36514123, 2022). "Glaucoma commonly co-exists with dementia and both conditions appear to share Apolipoprotein E genetic risk factors and a predilection for loss of retinal ganglion cells." (PMID 35688899, 2022). "The associations were consistently stronger among individuals with a lower genetic risk for dementia based on APOE-ε4 carrier status." (PMID 36125811, 2022). "Analyses stratifying by APOE ε4 status suggested that extreme sleep duration, lower sleep efficiency, and prolonged sleep latency were significantly associated with dementia only in APOE ε4 allele carriers." (PMID 34979998, 2022).
dementia (continued). "GRS constructed using these risk alleles, including APOE have been used to predict dementia and are correlated with cognitive test scores, cortical thickness and hippocampal and amygdala volume as well as atrophy in basal forebrain and temporal atrophy." (PMID 36477264, 2022). "We found evidence of a higher risk for dementia in people of self-defined Black ethnicity which remained even after adjusting for all 12 included risk factors but was eliminated when APOE status was adjusted for." (PMID 36223334, 2022). "The associations with dementia-causing diseases were largely attributable to three SNPs within 500 kb from the APOE region, whereas associations with autoimmune diseases were independent of APOE." (PMID 37118290, 2022). "In a secondary analysis of the effects of APOE-ε4 carriership on the RBC DHA relationship with all-cause dementia and AD, in three of the four interactions, our exploratory statistical significance threshold of 0.10 was met." (PMID 35745137, 2022). "Our study showed a significant association between the rs429358 polymorphism of the APOE gene and the diagnosis of dementia, which passed multiple comparison testing, with the C minor allele being a risk factor." (PMID 36421848, 2022). "The association between PPI use and incident all-cause dementia was observed particularly among the APOE ε4 heterozygous (+/−) population (HR, 1.46; 95% CI, 1.22–1.75; P < 0.001), and the interaction was statistically significant (P for interaction = 0.048)." (PMID 36045363, 2022). "To quantify genetic risk, we created a bivariate dosage scale that tested for the opposing effects of APOE ɛ2, often suspected to confer protective benefits, and ɛ4, classically believed to escalate dementia risk." (PMID 36512526, 2022). "Low plasma apoE levels are associated with impaired cognition and brain pathology and increased risk to develop dementia." (PMID 35884888, 2022). "In Cox proportional hazards models adjusted for age, sex, ethnicity, education, socioeconomic status, and APOE-ε4 carrier status, multimorbidity was associated with an increased risk of incident dementia (hazard ratio [HR], 1.63 [95% CI, 1.55-1.71])." (PMID 36125811, 2022). "The finding of this large population-based cohort study indicates that the use of proton pump inhibitors is associated with an increased risk of incident dementia, particularly among APOE ε4 heterozygotes." (PMID 36045363, 2022). "Previous findings have shown that non-standard visuomotor performance is impaired in individuals with specific dementia risk factors (family history of dementia and presence of the APOE ε4 allele) in advance of any cognitive impairments." (PMID 36533177, 2022). "The association of MP-MRI parameters and APOE-ε4 gene with VCIND patients who developed dementia was further investigated." (PMID 35317127, 2022). "Each 50 g/day higher total dairy intake was associated with 5% (95% CI 1%, 8%) higher multivariable-adjusted risk of incident dementia among the APOE-ε4 carriers (P-interaction 0.03)." (PMID 35217900, 2022). "The aim of this study was to investigate potential interactions between dietary patterns and genetic factors modulating risk for AD (i.e., APOE ε4 status and non-APOE AD-PRSs) in relation to incident dementia among 70-year-olds." (PMID 34632537, 2022). "The apolipoprotein E (APOE) gene is the strongest genetic factor modulating risk for AD and dementia." (PMID 34632537, 2022). "In fact, APOE ε4 emerged as a significant risk factor, increasing the susceptibility to develop dementia (OR = 2.527; p = 0.031)." (PMID 39081475, 2022). "This was anticipated based on prior work showing both higher levels of amyloid PET7,11,12,17–24,56–61 and APOE ɛ413,24,57,62–69 are associated with cognitive decline and dementia." (PMID 35310829, 2022). "Among the studied risk factors, the ε4 allele of the ApoE genotype is the persistently significant factor to predict dementia throughout all age groups." (PMID 36578446, 2022).